TNF (tumor necrosis factor)
Diseases named in the same sentence as TNF in open-access papers (continued):
Sharing a sentence is not in itself a finding about the gene and the disease.
Obesity (continued). "Authors revealed that tumor necrosis factor alpha (TNF-α), produced by adipose tissue, is a significant mediator of insulin resistance in the context of obesity." (PMID 40933372, 2025). "In mice with high-fat diet-induced obesity, TJT reduces the gene expression of sterol regulatory element-binding protein and tumor necrosis factor-α (TNF-α), which play critical roles in lipid and glucose metabolism." (PMID 41471332, 2025). "A total of 14 RCTs (13 two-arm and 1 four-arm) reported improvements in TNF-α outcome indicators for patients with T2DM and overweight or obesity." (PMID 40842495, 2025). "Inflammatory cytokines like Tumor necrosis factor (TNF)-α, chronically released in obesity, activate pathways that can lead to IR." (PMID 41143244, 2025). "This inflammatory response increases the secretion of proinflammatory cytokines, including tumor necrosis factor (TNF), interleukin-6 (IL-6), and leptin, while levels of insulin-like growth factor-1 (IGF-1) typically decrease with age and obesity." (PMID 41156491, 2025). "By lowering the expression of target genes, such as those involved in inflammation (e.g., adiponectin, (TNF-α), leptin, and TLR 4), obesity treatment leads to the prevention of NF-kB activation." (PMID 40242447, 2025). "In obesity, type 2 diabetes, and Parkinson’s disease, HIIT effectively lowers TNF-α and alleviates chronic inflammation." (PMID 40777031, 2025). "It is known that VF releases proinflammatory cytokines, such as TNF-α and IL-6, which increase bone resorption, decreases BMD, and it was shown that postmenopausal women with obesity who also have visceral adiposity have lower osteocalcin levels." (PMID 40854969, 2025). "Several key inflammatory markers have been reported to involve in obesity-induced inflammatory responses, including CRP, IL-6, and tumor necrosis factor-α (TNF-α)." (PMID 40568560, 2025). "For example, obesity was characterized by systemic low-grade chronic inflammation, marked by elevated levels of CRP, IL-6, IL-8, and tumor necrosis factor-α (TNF-α) in the serum." (PMID 40612555, 2025). "Elevated levels of pro-inflammatory cytokines, including tumor necrosis factor-α (TNF-α) and interleukin-6 (IL-6), were observed in Zn-overloaded states, further exacerbating obesity-related complications." (PMID 41459237, 2025). "Basal cytokine production (IFN-γ, TNF-α, IL-4) was also significantly and specifically increased in CD4− (CD8+) iNKT cells from individuals with obesity compared to lean individuals." (PMID 41000378, 2025). "Adipose tissue-derived cytokines such as tumor necrosis factor-α (TNF-α) and adipokines play a role in AGE metabolism and clearance, and their dysregulation in obesity can contribute to elevated AGE levels." (PMID 40517170, 2025). "In a study involving patients with obesity and type 2 diabetes, the administration of PSO for 8 weeks resulted in significant reductions in serum levels of IL-6 and TNF-α." (PMID 40724233, 2025). "Prior studies also highlight the crucial importance of obesity and elevated adipose tissue in the development of IR and T2DM, which is partly due to the production of FFA and TNF-α and interleukins by the adipose tissue." (PMID 41268155, 2025). "TNF-α mRNA was significantly upregulated in HFD-fed rats compared to the control group (p < 0.0001 vs. control), consistent with obesity-induced inflammation." (PMID 40867531, 2025). "Pro-inflammatory cytokines, including TNF-α, IL-6, and IFN-γ, exhibit elevated levels in obesity cases and disrupt adipogenesis by impairing the function of transcriptional regulators such as PPARγ and C/EBPα." (PMID 40002389, 2025). "WAT also releases proinflammatory cytokine tumor necrosis factor (TNF)-α, which influences hyperinsulinemia in obesity, and proinflammatory cytokine interleukin (IL)-6, which produces free fatty acids (FFAs), causing poor glucose and liver metabolism." (PMID 40301996, 2025).
Obesity (continued). "Overweight and obesity are directly correlated with enhanced inflammatory processes through the occurrence of TNF, TNF-α, or IL-1β." (PMID 40427034, 2025). "Of note, it was shown that increased acetylation of H3K9 and H3K18 at the TNF gene and decreased H4 acetylation at the GLUT4 gene were correlated with a chronic inflammatory state, hyperglycaemia, and obesity development." (PMID 41155431, 2025). "Exercise interventions (aerobic, resistance, and combined training) can significantly reduce obesity indicators including WC, BMI, and BF%, while lowering levels of inflammatory markers such as CRP, TNF-α, and IL-6." (PMID 41561801, 2025). "Tumoral necrosis factor α (TNFα) and IL-1β have been proven as mediators for LGCI in obesity, since targeted antibody neutralization improves metabolic balance." (PMID 40868832, 2025). "The significantly increased levels of IL‐1β, IL‐6, and TNF‐α, in HFD‐fed mice are consistent with the well‐established link between obesity and chronic low‐grade inflammation, often referred to as “metaflammation”." (PMID 41245183, 2025). "When infected with influenza A, the adipose tissue of two mouse models of obesity produced increased levels of MCP-1, TNFα, IL-6, and TGFβ." (PMID 40386706, 2025). "Dairy products and dairy proteins have demonstrated efficacy in reducing inflammatory markers, including CRP, IL-6, TNF-α, and MCP-1, in individuals with obesity and overweight conditions." (PMID 40216734, 2025). "It is suspected that this is related to significantly increased pro-inflammatory factors like tumor necrosis factor-α (TNF-α) and interleukin-1 (IL-1) in obesity." (PMID 40149608, 2025). "PAI-1 stimulates inflammatory pathways (including increasing the production of TNF-α) and decreases the expression of PPAR-γ, and promoting insulin resistance and obesity." (PMID 41341131, 2025). "In obesity, however, APC differentiation is dysregulated by increased exposure to pro-inflammatory cytokines (e.g., TNF-α, IL-6) and fibrotic signals, such as transforming growth factor-beta (TGF-β)." (PMID 40699742, 2025). "With increasing obesity in IBD cohorts, prospective trials in this area, particularly for anti-TNFα drugs, would be welcomed." (PMID 41302991, 2025). "The rapid reduction in IL-1β and TNF-α after 1 month of use of the intervention composition suggests a safe and effective novel strategy for reducing pro-inflammatory cytokines that may offer an opportunity to diminish the inflammatory status in patients with overweight/pre-obesity." (PMID 40430061, 2025). "Obesity can skew the adipose tissue to secrete adipokines, including MCP-1, TNF-α, IL-1β, and IL-6, which perpetuate a low-grade inflammation or meta-inflammation." (PMID 41472730, 2025). "In turn, individuals with obesity exhibited lower CAMKK1, lower glycemia, lower TNFα and higher ghrelin and leptin in comparison to patients with T2DM." (PMID 40965347, 2025). "Pro-inflammatory cytokines (e.g., TNF-α, IL-1β, IL-6, MCP-1) contribute to metabolic disorders such as obesity and diabetes." (PMID 40573106, 2025). "In fact, obesity can impact serum concentrations of pro-inflammatory mediators [such as IL-6, CRP, TNF-α, resistin, and leptin] and anti-inflammatory mediators (Adiponectin and IL-10) in individuals with periodontitis." (PMID 40422620, 2025). "In contrast, EATs of patients with obesity or T2DM have higher numbers of CD4+ T and B cells and pro-inflammatory cytokines, such as IL-1, IL-6, TNF-α and IFN-γ." (PMID 40592472, 2025). "Individuals exhibiting frailty often display elevated levels of Interleukin-6 (IL-6), C-reactive protein (CRP), and Tumor Necrosis Factor-alpha (TNF-α), partially attributed to the prevalence of overweight/obesity in the elderly population." (PMID 40413725, 2025). "In obesity-related PCOS, heightened leptin levels and increased circulating TNF-α further alter EV cargo composition towards pro-inflammatory and anti-differentiation patterns, worsening oocyte maturation abnormalities." (PMID 41010046, 2025).
Obesity (continued). "Inhibited iNOS and TNF-α, reduced ROS and intracellular Ca2+, blocked PKC-α and NF-κB, showing strong anti-inflammatory and antioxidant effects relevant for obesity." (PMID 40733199, 2025). "Inflammatory markers, including CD16, CD11c, CCR2, CCR5, TNF-α, IL-1β, IL-2, IL-12, CCL8, CCL19, and CXCL9, were positively correlated with IL-23 in the AT-compartment in the obesity context." (PMID 41158638, 2025). "Obesity‐related type I inflammatory cytokines (e.g., IFN‐γ, TNF, leptin, insulin, and palmitic acid) promote TAM PD‐1 expression through mechanistic target of rapamycin complex 1 (mTORC1) and glycolysis‐dependent mechanisms." (PMID 41267926, 2025). "miR-130a-3p which also plays a cardioprotective role by reducing TNF-α, IL-6, VCAM-1, ICAM-1 and E-selectin expression is downregulated by hyperglycemia and obesity." (PMID 40696355, 2025). "Inflammation, particularly involving interleukin-6 (IL-6) and tumor necrosis factor-alpha (TNF-α), plays a crucial role in the pathogenesis of obesity and T2DM." (PMID 40842495, 2025). "Our results highlight the overexpression of TNFα and IL-1β in the obesity group, while the CRP was significantly higher on the obesity group compared to the controls; this correlates with the elevated BMI and low plasma iron distribution in the obese patients." (PMID 39057082, 2024). "For instance, SM (60 mg/kg) was illustrated to reduce inflammation (TNF-α, IL-1β and IL-6) and to mitigate liver damage and insulin resistance in a model of HFD-induced obesity mice." (PMID 38247522, 2024). "Modulation by pro-inflammatory cytokines such as interleukin (IL-6) and tumor necrosis factor-alpha (TNF-α), as well as anti-inflammatory drugs, suggests that nesfatin plays a role in obesity and inflammation." (PMID 39455994, 2024). "Our research suggested that the amelioration of IO on obesity, glycolipid metabolism, proteinuria, podocyte injury in ORG mice via its modulation on TNF signal, and triterpenoids were predicated as acting components." (PMID 39234117, 2024). "This study aims to investigate the effects of low-fat diet on liver enzymes and serum levels of inflammatory cytokines such as chemerin, IL-6, TNF-α, and myokines such as irisin, FGF-21 in individuals with overweight, obesity and NAFLD." (PMID 38608067, 2024). "Based on our DA data, human SGBS adipocyte EVs exhibited different FA profiles under TNFα, PA, and EPA treatments, stimuli relevant to nutrition, obesity-induced inflammation, or potential resolution promoted by EPA." (PMID 38965596, 2024). "Pro-inflammatory factors like tumor necrosis factor α (TNF-α) and IL-1β reduce NRG4 expression in adipocytes, likely contributing to the reduced NRG4 in obesity." (PMID 39872218, 2024). "The significant increase in TNF-α in both the HF and HFHS groups confirms the progression of low-grade inflammation, which is a common feature in obesity." (PMID 39199499, 2024). "Dysfunctional endothelial cells release more IL-6, TNF-α, and PAI-1 and VWF, which induce highly inflammatory and procoagulant states in patients with obesity." (PMID 39199353, 2024). "Patients with obesity showed elevated levels of circulating ferritin, C-reactive protein (CRP), and tumor necrosis factor-a (TNF-a) upon admission." (PMID 39057109, 2024). "Meanwhile, in obesity, saturated fatty acids induce the ATM to polarize to an M1 phenotype, producing IL-6, TNF-α, IL-12, and IL-1β, among other inflammatory factors contributing to the impairment of insulin signaling and promoting IR." (PMID 38610754, 2024). "Adipocytes also contribute to the development of obesity-induced inflammation by increasing the secretion of MCP-1, TNF-α, and IL-6." (PMID 39609876, 2024). "The administration of COST resulted in the reduction of TNF-α, IL1-β, and IL-6 levels in an obesity cardiomyopathy mouse model." (PMID 38629103, 2024).
Obesity (continued). "Our current study shows that HFD-induced obesity exacerbates allergic asthma via the action of different cytokines (IL-17, TGF-β, TNFα, and IL-1β) known to regulate lung damages and neutrophilic inflammation." (PMID 38892358, 2024). "In this way, the results observed for TNF-α and MMP-2-d are acceptable since people with some age, chronic inflammation, and obesity showed high levels of the parameters evaluated when compared to healthy individuals." (PMID 38470620, 2024). "Moreover, obesity is frequently characterized as a systemic, chronic, low-grade inflammatory condition, leading to an upregulation in the expression of pro-inflammatory cytokines like interleukin-1 and tumor necrosis factor-α in the adipose tissue of obese individuals." (PMID 38475782, 2024). "mtDNA copy number positively correlated with basal and LPS-stimulated TNF-α secretion, the most significant correlation was found in the group of patients with CHD and obesity." (PMID 38572445, 2024). "So far there are no studies on the connection between leukocyte and plasma expression of MMPs and TIMPs with inflammatory markers of obesity including circulating levels of resistin, AST, ALT and TNF-alpha." (PMID 38541059, 2024). "After 3 months, reductions in TNF-α, IL-6, and FGF-21 levels were significant in individuals with obesity/overweight and NAFLD." (PMID 38608067, 2024). "The release of tumor necrosis factor (TNF)-α, interleukin (IL)-1, and IL-6, proinflammatory cytokines, and chemokines is heightened in obesity-related inflammation." (PMID 39328456, 2024). "Accumulated data confirmed the ameliorative effects of SM in adipose tissue inflammation (decreased expression of IL-1β and TNF-α and increased expression of IL-10 and adiponectin) in an HFD-induced obesity model in mice." (PMID 38247522, 2024). "Through NFκB-mediated production of the inflammatory mediator TNFα, which upregulates the expression of c-fms, RANK, and RANKL, obesity enhances osteoclastogenesis." (PMID 39019936, 2024). "The overexpression of TNF-α, MAPK, and AKT protein was confirmed in the VAT of patients with obesity." (PMID 39484291, 2024). "A study by Alzamil found that TNF-α was significantly higher in individuals with obesity and T2DM, and that TNF-α was positively correlated with HOMA-IR and HbA1c." (PMID 39519417, 2024). "Inflammatory cytokines such as tumor necrosis factor-alpha (TNF-α), CRP, and interleukins (IL-6, IL-18), along with resistin and visfatin, are dysregulated in obesity." (PMID 38910676, 2024). "Chronic inflammation is a biological feature of aging and is increased in obesity, with biomarkers such as C-reactive protein (CRP), interleukin-1B/6, and tumor necrosis factor-alpha (TNF-α) increasing with age." (PMID 39339652, 2024). "A previous study reported that increasing levels of TNFα and IL1β impairs the phosphorylation of IRS1/2 via severe mechanisms (MAPK, JNK and IKK) in obesity, resulting in insulin resistance in liver and adipose tissues." (PMID 38338579, 2024). "In obesity, inflamed and dysfunctional adipocytes within WAT release pro-inflammatory cytokines (TNF-α, IL-6, IL-8, and MCP-1) and attract immune cells such as macrophages, mast cells, and lymphocytes, further amplifying the immune response." (PMID 40474934, 2024). "Regarding the correlation analyses of RAS components with hepatic cytokines in individuals with obesity and MASLD, a significant positive correlation was observed between ACE, and all analyzed cytokines (TNF-α, IL-6, IL-4, IL-13, IL-10)." (PMID 39337863, 2024). "Our main objective was to evaluate the levels of adiponectin, leptin, TNFα, IL6, IGFs 1 and 2 in endometrial cancer patients compared to control patients and to examine their relationship with obesity." (PMID 38339282, 2024).
Obesity (continued). "TNF‐α, released by EAT in obesity, was also demonstrated to enhance adipocyte angiotensinogen protein expression and angiotensin II secretion, providing further evidence of the link between obesity and renin‐angiotensin‐aldosterone system activation." (PMID 38156451, 2024). "The direct association of changes in the number of mtDNA copies and the secretion of TNF-α by monocytes in individuals with CHD and obesity was revealed in the current study." (PMID 38572445, 2024). "During the progression of obesity, adipocytes play a role in promoting inflammation by releasing typical proinflammatory cytokines, including IL-1, IL-6, COX-2, and TNF-α." (PMID 39281480, 2024). "In the state of obesity, adipose tissue releases various chemokines and inflammatory factors, including MCP-1, TNF-α, IL-1β, and IL-6." (PMID 39334887, 2024). "In a fructose-induced obesity model, SPX injection was found to significantly reduce the levels of pro-inflammatory cytokines (TNF-α, IL-1β, and IL-6) in the epididymal adipose tissue of mice." (PMID 38234666, 2024). "In addition, the capacity of probiotics to regulate HDL-cholesterol, LDL-cholesterol, adiponectin, leptin, and TNF-α, as well as regulate lipid metabolism and reduce inflammation, was demonstrated in a systematic review studying the effects of probiotics in children with obesity." (PMID 39596385, 2024). "In obesity, free fatty acids released from adipocytes bind to toll-like receptor 4 (TLR4), promoting proinflammatory cytokine TNF-α, and induce chronic inflammation." (PMID 38396804, 2024). "Adipose-derived stem cells (ASCs) from human subjects with obesity have been demonstrated to enhance IL-17 release by Th17 cells but inhibit the expression of IFN-γ and TNF-α by Th1 cells." (PMID 38455510, 2024). "Obesity is considered a chronic inflammatory state, with adipocytes secreting inflammatory cytokines such as IFN-γ, TNFα, and IL-1β." (PMID 38898891, 2024). "Circulating MAITs in obesity and metabolic disease are characterized by increased IL2, granzyme B, IL17, IFNγ, and TNFα, and less IL10 compared to healthy controls." (PMID 38674935, 2024). "On the other hand, the same authors report levels of TNF-α and MCP-1 between 13.18 and 23.71 ng/mL; all these adipokines are related to the development of chronic inflammation and metabolic disorders during obesity." (PMID 39769396, 2024). "We investigated the contributions of adipose progenitors (ASCs) and adipocytes (AMCs) to TNFα-induced ECM remodeling and a possible implication of irisin in AT impairment in obesity." (PMID 37569456, 2023). "IM and NCM are a major source of the inflammatory cytokines TNF‐alpha (TNF‐α) and interleukin‐6 (IL‐6), and proportions of IM and NCM are elevated with obesity and other inflammatory diseases including CVD." (PMID 38011590, 2023). "After polyunsaturated fatty acid consumption, there would be a correlation between obesity and inflammation, decreasing pro-inflammatory genes and cytokines expression, such as VCAM-1, 8-epi-prostaglandin-F2α (8-EPI), and TNF-α." (PMID 38024342, 2023). "Therefore, a key link in the negative association between CD34+ cell count and obesity could be TNFα, one of the most important inhibitors of haematopoiesis in the bone marrow, both in the basal state and after G-CSF stimulation." (PMID 37895025, 2023). "Furthermore, anti-obesity and insulin sensitizing effects have also been endorsed by the modulating potential of C. odorata and coumarin on adipokinin levels (leptin, adiponectin, and chemerin), and inflammatory (TNFα, IL-6) and oxidative stress biomarkers (CAT, SOD, MDA)." (PMID 37033655, 2023). "A state of chronic inflammation, typical of conditions like obesity, T2DM, and MetS, is distinguished by the augmented expression of inflammatory adipokines, such as IL-6 and TNF-α." (PMID 37958602, 2023).